MSC (musculin)
Description:
Transcription repressor capable of inhibiting the transactivation capability of TCF3/E47. May play a role in regulating antigen-dependent B-cell differentiation.
Synonyms: ABF-1; bHLHa22; ABF1; MYOR
Tractability: PROTAC: ubiquitination databases record sites on it.
Gene: Protein-coding gene on chromosome 8 (71,841,552 to 71,844,496, reverse strand). Ensembl gene ENSG00000178860.
Subcellular location: Nucleus
Subcellular location (Human Protein Atlas): Nucleoplasm
Gene Ontology:
Molecular function: protein binding; RNA polymerase II cis-regulatory region sequence-specific DNA binding; sequence-specific double-stranded DNA binding; DNA-binding transcription factor activity; DNA-binding transcription factor activity, RNA polymerase II-specific; RNA polymerase II transcription regulatory region sequence-specific DNA binding; DNA-binding transcription repressor activity, RNA polymerase II-specific; protein dimerization activity
Biological process: cardiac conduction system development; regulation of DNA-templated transcription; regulation of transcription by RNA polymerase II; skeletal muscle tissue development; branchiomeric skeletal muscle development; diaphragm development; negative regulation of transcription by RNA polymerase II; roof of mouth development
Cellular component: nucleoplasm; chromatin; nucleus
Genetic constraint (gnomAD): Loss-of-function variants: 16 observed, 13.09 expected, observed/expected ratio (o/e) 1.22, 90% interval 0.82 to 1.78. The synonymous counts are far from expectation, so gnomAD's model fits this gene poorly and the ratio says little. Missense variants: 320 observed, 278.13 expected, observed/expected ratio (o/e) 1.15, 90% interval 1.05 to 1.26. Synonymous variants: 165 observed, 124.77 expected, observed/expected ratio (o/e) 1.32, 90% interval 1.16 to 1.5.
Homologues: Orthologues: chimpanzee MSC (100% identical), macaque MSC (99% identical), pig MSC (93% identical), dog MSC (90% identical), guinea pig MSC (90% identical), rabbit MSC (90% identical), mouse Msc (84% identical), rat Msc (77% identical), zebrafish msc (51% identical), tropical clawed frog msc (49% identical), Drosophila melanogaster HLH54F (30% identical), Drosophila melanogaster CG33557 (18% identical), and 3 more. Paralogues in human: TCF21 (54% identical), TCF15 (27% identical), TCF24 (25% identical), SCX (25% identical), HAND2 (22% identical), TCF23 (22% identical), TWIST1 (22% identical), HAND1 (21% identical), TWIST2 (21% identical), PTF1A (20% identical), FIGLA (17% identical), FERD3L (17% identical), and 1 more.
Diseases named in the same sentence as MSC in open-access papers:
MSC is named in the same sentence as 13 diseases in open-access papers, as found by Europe PMC text mining. Sharing a sentence is not in itself a finding about the gene and the disease. The quoted sentences say what the papers report.
rhabdomyosarcoma (5 papers, 2013 to 2024). A rare aggressive malignant mesenchymal neoplasm arising from skeletal muscle. "In addition, musculin has been shown to inhibit myogenesis and block differentiation in rhabdomyosarcoma cells." (PMID 34553752, 2022). "Musculin (MSC) is a basic helix-loop-helix transcription factor that inhibits myogenesis during normal development and contributes to the differentiation defect in rhabdomyosarcoma." (PMID 24175993, 2013). "A repressive basic helix-loop-helix factors, musculin (MSC), antagonize the activity of MYOD in myoblasts and in rhabdomyosarcoma." (PMID 30119689, 2018). "The myogenic bHLH inhibitor musculin binds widely throughout the genome in RD rhabdomyosarcoma cells and has a broadly overlapping, but non-identical, set of binding sites and peaks as MyoD." (PMID 24175993, 2013).
gastric cancer (1 paper, 2024). A primary or metastatic malignant neoplasm involving the stomach. "Musculin (MSC) DNA methylation plays a role in gastric carcinogenesis and holds potential as a valuable biomarker for diagnosing gastric cancer (GC) and detecting recurrence." (PMID 38785978, 2024).
hepatocellular carcinoma (1 paper, 2021). A malignant tumor that arises from hepatocytes. "For example, Musculin (MSC) has been regarded as a component of a robust gene signature identified using a risk score model, and has been considered to be potential immunotherapy targets for hepatocellular carcinoma." (PMID 34903206, 2021).
Hodgkins lymphoma (1 paper, 2013). A heterogeneous group of malignant lymphoid neoplasms of B-cell origin characterized histologically by the presence of Hodgkin and Reed-Sternberg (HRS) cells in the vast majority of cases. "MyoR/ABF-1 is coded by the musculin (msc) gene and has been independently identified in mouse skeletal muscle precursors (MyoR for Myogenic Repressor, and in Hodgkin lymphomas and Epstein-Barr virus-transformed B-cell lines (ABF-1, Activated B cell Factor-1." (PMID 24386375, 2013).
Hyperglycemia (1 paper, 2017). An increased concentration of glucose in the blood. "Our results show that the inhibition of MsC with Gd3+ did not affect the time course of biphasic AP-induced Ca2+ transients during acute hyperglycemia." (PMID 28835899, 2017).
leukemia (1 paper, 2021). A malignant (clonal) hematologic disorder, involving hematopoietic stem cells and characterized by the presence of primitive or atypical myeloid or lymphoid cells in the bone marrow and the blood. "Among the other genes with strong correlations between DNA methylation and gene expression, aberrant DNA methylation and downregulation of FKBP9, CA8, MSC, TRPC6, ZNF492, ZNF229, and ZNF471 genes in leukemia patients are reported here for the first time." (PMID 34575904, 2021).
Meckel syndrome (1 paper, 2025). "We co-expressed this integrated, multicopy mNG::PLCδ1-PH transgene with mScarlet-tagged MKS-2 (MKS-2::mSc), a protein in the Meckel syndrome (MKS) complex that localizes to the TZ." (PMID 41064964, 2025).
Parkinson disease (1 paper, 2024). A progressive degenerative disorder of the central nervous system characterized by loss of dopamine producing neurons in the substantia nigra and the presence of Lewy bodies in the substantia nigra and locus coeruleus. "The DisGeNET database labels NLRP1, MSC, PTK2B, TAC1 and FOSL2 as genes associated with Parkinson’s disease, with association scores of 0.964, 0.944, 0.907, 0.889 and 0.888, respectively." (PMID 38350848, 2024).
MSC also shares sentences with these, for which no sentence is quoted: infection (3 papers); malaria (2); cerebral infarction (1); colitis (1); COVID-19 (1).